CHST2 (carbohydrate sulfotransferase 2)
Description:
Sulfotransferase that utilizes 3'-phospho-5'-adenylyl sulfate (PAPS) as sulfonate donor to catalyze the transfer of sulfate to position 6 of non-reducing N-acetylglucosamine (GlcNAc) residues within keratan-like structures on N- and O-linked glycans and within O-linked mucin-type glycans. Selectively transfers the sulfate group onto the terminal GlcNAc of alpha1,3-Man or alpha1,6-Man antenna of complex-type N-glycans depending on glycan composition. Only sulfates terminal GlcNAc of alpha1,3-Man antenna of G0 complex-type N-glycans. Can sulfate keratan-type N-acetyllactosamine (LacNAc) repeats generating epitopes for self versus non-self immune recognition by C-type lectins. Transfers the sulfate group primarily on core 2 GlcNAcbeta1-6(Galbeta1-3)GalNAcalpha-Ser/Thr and with lower efficiency on extended core 1 GlcNAcbeta1-3Galbeta1-3GalNAcalpha-Ser/Thr based O-linked glycans on peripheral node addressins (PNAds) expressed on the lumenal side of high endothelial venules (HEVs). Shares substrate specificity with CHST4 and both contribute to generate sialyl 6-sulfo Lewis X determinant (also known as MECA-79 epitope) for SELL recognition, a prerequisite for continuous lymphocyte homing into peripheral lymph nodes and antigen immune surveillance (By similarity). Has no activity toward alpha-linked GlcNAc moiety exposed at the non-reducing ends or to internally located GlcNAc residues.
Synonyms: GST-2; GlcNAc6ST-1; Gn6ST-1; C6ST; GST2; HEL-S-75
Tractability: Antibody: UniProt predicts a signal peptide or a membrane-spanning region. PROTAC: ubiquitination databases record sites on it; its protein half-life has been measured.
Gene: Protein-coding gene on chromosome 3 (143,119,771 to 143,124,014, forward strand). Ensembl gene ENSG00000175040.
Subcellular location: Golgi apparatus, trans-Golgi network membrane
Subcellular location (Human Protein Atlas): Golgi apparatus; Cytosol; Nucleoplasm
Pathways (Reactome):
Metabolism: Keratan sulfate biosynthesis
Gene Ontology:
Molecular function: N-acetylglucosamine 6-O-sulfotransferase activity; sulfotransferase activity
Biological process: N-acetylglucosamine metabolic process; sulfur compound metabolic process; inflammatory response; keratan sulfate proteoglycan biosynthetic process; positive regulation of leukocyte tethering or rolling; carbohydrate metabolic process
Cellular component: Golgi apparatus; trans-Golgi network; Golgi membrane
Genetic constraint (gnomAD): Loss-of-function variants: 23 observed, 28.33 expected, observed/expected ratio (o/e) 0.81, 90% interval 0.58 to 1.15. The synonymous counts are far from expectation, so gnomAD's model fits this gene poorly and the ratio says little. Missense variants: 720 observed, 682.03 expected, observed/expected ratio (o/e) 1.06, 90% interval 0.99 to 1.12. Synonymous variants: 392 observed, 313.08 expected, observed/expected ratio (o/e) 1.25, 90% interval 1.15 to 1.36.
Homologues: Orthologues: chimpanzee CHST2 (100% identical), macaque CHST2 (99% identical), rabbit CHST2 (96% identical), guinea pig CHST2 (96% identical), dog CHST2 (95% identical), mouse Chst2 (95% identical), rat Chst2 (95% identical), pig CHST2 (83% identical), tropical clawed frog chst2 (60% identical), zebrafish chst2b (56% identical), zebrafish chst2a (53% identical), Drosophila melanogaster CG31637 (20% identical), and 1 more. Paralogues in human: CHST7 (38% identical), CHST5 (27% identical), CHST6 (27% identical), CHST4 (25% identical), CHST1 (24% identical), CHST3 (21% identical).
Diseases named in the same sentence as CHST2 in open-access papers:
CHST2 is named in the same sentence as 18 diseases in open-access papers, as found by Europe PMC text mining. Sharing a sentence is not in itself a finding about the gene and the disease. The quoted sentences say what the papers report.
breast carcinoma (2 papers, 2023 to 2025). "Here, we report identification of a gene encoding the key GlcNAc sulfation enzyme CHST2 is induced by Snail in multiple breast cancer cells." (PMID 37095090, 2023). "In conclusion, our observations shed light on the molecular mechanisms underlying Snail transactivating CHST2 transcription and expression and elaborate the role of Snail-CHST2 axis in mediating sulfation of sialyl LewisX on the cell surface during breast cancer metastasis." (PMID 37095090, 2023). "In our study, we tried to elucidate the biological role of 6-sulfation sialyl LewisX in breast cancer and discovered cell surface 6-sulfo sialyl LewisX synthesis mediated by CHST2 is associated with breast cancer metastasis and may be a potential novel breast cancer metastatic marker." (PMID 37095090, 2023). "Current findings demonstrate Snail induces CHST2 transcription, which results in cell surface 6-sulfo sialyl LewisX synthesis increase and facilitates migration and metastasis of breast cancer cells." (PMID 37095090, 2023). "Taken together, these data suggest that the Snail-CHST2 axis mediated breast cancer migration by increasing MECA79 antigen synthesis." (PMID 37095090, 2023). "Conversely, overexpression of CHST2 increased breast cancer cell migration and metastasis in vitro and in vivo." (PMID 37095090, 2023). "To explore the role of CHST2 in breast cancer progression, we first depleted CHST2 in MDA-MB-231 cells by stably expressing specific targeting shRNAs, subsequently, CHST2 protein levels were examined by Western blot assays." (PMID 37095090, 2023). "Our experiments clearly show that CHST2 is responsible for MECA79 antigen synthesis in breast cancer cells." (PMID 37095090, 2023). "Collectively, these findings demonstrated that CHST2 is essential for breast cancer cell migration and elevated CHST2 expression promotes breast cancer metastasis." (PMID 37095090, 2023). "Collectively, these data provide novel insights into the biology of Snail/CHST2/MECA79 axis in breast cancer progression and metastasis as well as potential therapeutic strategy for the diagnosis and treatment of breast cancer metastasis." (PMID 37095090, 2023). "Here, we reported that Snail-induced expression of CHST2 in breast cancer cells is responsible for 6-sulfo sLeX synthesis, which mediates breast cancer metastasis." (PMID 37095090, 2023). "To further explore the role of CHST2 in breast cancer metastasis in vivo, we performed tail-vein injection of MDA-MB-231 cells with vector control, CHST2 knockdown or overexpression into BALB/C nude mice to generate lung metastasis models." (PMID 37095090, 2023). "High expression of CHST2 results in increased sulfation modifications of glycan determinants in breast cancer cells." (PMID 37095090, 2023). "Collectively, these data suggest that CHST2-mediated breast cancer cell migration and metastasis are dependent on cell surface MECA79 antigen synthesis." (PMID 37095090, 2023). "Consistent with our findings, analysis of The Cancer Genome Atlas (TCGA) database revealed a significant positive correlation between Snail and CHST2 expression levels in 1095 breast cancer specimens." (PMID 37095090, 2023). "Biologically, CHST2 depletion results in inhibition of breast cancer cell migration and metastasis, while overexpression of CHST2 promotes cell migration and lung metastasis in nude mice." (PMID 37095090, 2023). "High expression of CHST2 promoted the migration and metastasis of breast cancer cells." (PMID 41013841, 2025). "Furthermore, Snail-CHST2 axis mediated sulfation of sialyl LewisX is probably the downstream target to facilitate breast cancer metastasis." (PMID 37095090, 2023). "Here, we examined the CHST2 substrate in breast cancer cells." (PMID 37095090, 2023). "We therefore investigated whether CHST2 enzyme activity affects its function in facilitating breast cancer migration." (PMID 37095090, 2023).
breast carcinoma (continued). "In this study, we report that the expression of CHST2 contributes to breast cancer metastasis." (PMID 37095090, 2023). "Furthermore, to examine whether CHST2 expression influences breast cancer cell growth, cell proliferation assays were conducted in breast cancer cells with CHST2 knockdown or overexpression." (PMID 37095090, 2023). "Furthermore, in order to determine whether cell surface MECA79 antigen synthesis by CHST2 is responsible for mediating breast cancer cell migration and to evaluate whether targeting MECA79 antigen could be an effective strategy in inhibition of cancer cell migration." (PMID 37095090, 2023). "We discovered breast cancer cell migration and metastasis reduced after depleted CHST2, while cell proliferation is not affected." (PMID 37095090, 2023). "In the present study, we have revealed that the expression of CHST2 is induced by Snail in breast cancer cells, while CHST4 expression is not affected by Snail." (PMID 37095090, 2023). "However, the role of CHST2-mediated sulfation process in breast cancer has not yet been reported." (PMID 37095090, 2023).
Burkitt lymphoma (2 papers, 2019 to 2022). A rare form of malignant mature B-cell non-Hodgkin lymphoma. "Transfer of a sulfate residue to GlcNAc residues in keratan sulfate by CHST2 has been revealed to activate the p38 MAPK-PI3K (mitogen-activated protein kinase/phosphatidylinositol 3-kinase) cell signaling pathway and decrease cell apoptosis caused by radiation in Burkitt’s lymphoma cells." (PMID 35267472, 2022). "Moreover, transfer of a sulfate residue to position 6 of GlcNAc residues in KS by CHST2/6/7 has been reported to activate p38 MAPK-PI3K cell survival signaling pathway axis and reduced radiation induced apoptosis in Burkitt’s Lymphoma cells." (PMID 31273306, 2019).
acute lymphoblastic leukemia (1 paper, 2021). Leukemia with an acute onset, characterized by the presence of lymphoblasts in the bone marrow and the peripheral blood. "CHST2 and CHST7 were used as biomarkers for pediatric high-risk B-precursor acute lymphoblastic leukemia, and patients with high CHST2 and CHST7 expression had poor 4-year relapse-free survival rates." (PMID 34288811, 2021).
allergic asthma (1 paper, 2010). A asthma with a basis in a pathological type I hypersensitivity reaction. "Because Th2 cells are prominent in asthma, especially allergic asthma, genes such as CHST2 that modulate Th2 cell differentiation are likely to play a role in asthma susceptibility." (PMID 20698975, 2010).
asthma (1 paper, 2010). "Even though CHST2 is a plausible candidate gene for asthma, rs17572584 is located downstream of this gene, and hence, further study is needed to find out whether the association we measured is stronger in SNPs located nearer or within the gene across multiple populations." (PMID 20698975, 2010).
prostate carcinoma (1 paper, 2024). A carcinoma that arises from epithelial cells of the prostate gland. "ACP3 is a prostatic acid phosphatase that also regulates prostate cancer cell growth by dephosphorylating ERBB2, which is a part of the adjacent network of our target gene CHST2 in our previous study that shows a slight negative correlation with TPS and deactivates MAPK-mediated signalling." (PMID 39457550, 2024).
tumor (4 papers, 2022 to 2025). "The complexity of signalling pathways and their interactions call for larger, more comprehensive datasets to accurately decipher the intricate dynamics of CHST2 and other relevant genes in tumour biology." (PMID 39063109, 2024). "Our integrative analysis revealed an elevated expression of CHST2 in GBM tumours, designating it as an unfavourable prognostic gene in GBM, as supported by data from two independent GBM cohorts." (PMID 39063109, 2024). "Delving deeper into the role of CHST2 in tumour biology through expanded datasets and integrative approaches could significantly improve GBM treatment strategies." (PMID 39063109, 2024). "We found that CHST2 and the well-known target genes of the proposed drugs, HRH1, and EGFR/ERBB2, were co-expressed in the GBM tumours as shown in iNetModels." (PMID 39063109, 2024). "Our previous observation of PNAd expression on both surfaces of tumor endothelium is consistent with the very low level of Chst4 expression in TEC, and suggests that Chst2 is largely responsible for synthesizing 6-sulfo-sialyl Lewis X in TEC." (PMID 36189308, 2022).
cancer (2 papers, 2023 to 2024). A tumor composed of atypical neoplastic, often pleomorphic cells that invade other tissues. "In addition, sodium chlorate treatment or catalytically inactive mutant can efficiently abolish CHST2 or Snail-mediated cancer cell migration." (PMID 37095090, 2023). "CHST2, SPACA6, and TSC22D1 had lower methylation levels in cancer tissues than Riplet and GNB4, in which CHST2 and TSC22D1 had higher methylation levels in normal tissues." (PMID 38154055, 2024). "However, the biology roles of CHST2 and MECA79 antigen in cancer progression remains poorly investigated and elusive." (PMID 37095090, 2023).
CHST2 also shares sentences with these, for which no sentence is quoted: Alzheimer disease (1 paper); Arthritis (1); leukemia (1); lymphoma (1); osteosarcoma (1); peripheral neuropathy (1); rheumatoid arthritis (1); skin tumor (1); spinal cord injury (1); thyroid cancer (1).